LGMN (legumain)
Diseases named in the same sentence as LGMN in open-access papers (continued):
Sharing a sentence is not in itself a finding about the gene and the disease.
tumor (continued). "Legumain is primarily a lysosomal enzyme, however, it has also been found on the cell surface and in membrane-associated vesicles concentrated along the invadopodia of tumor cells." (PMID 20074384, 2010). "Furthermore, it has been reported that an ethanol-soluble fraction of Andosan inhibits the activity of the tumor-associated protease, legumain, which may indirectly indicate an antitumor effect." (PMID 29238712, 2017). "Similarly, Legumain may represent a target for inhibition of growth and metastasis based on its up-regulation associated with tumor growth and unique restricted specificity." (PMID 24023813, 2013). "Because legumain is frequently overexpressed in tumor cells and tumor microenvironment macrophages, AAN linkers enable preferential activation within the tumor microenvironment, thereby reducing toxicity to normal tissues." (PMID 41590805, 2026). "Legumain, an asparaginyl endopeptidase enriched in tumor lysosomes, recognizes a specific peptide motif in the linker, ensuring that drug release occurs selectively in cells with high legumain activity." (PMID 41373734, 2025). "LGMN has been well recognized for its role in promoting tumor progression through distinct mechanisms in various types of cancers." (PMID 40131864, 2025). "The acidic pH of the tumor microenvironment facilitates the self-processing and maturation of legumain, enabling it to exert its asparagine endopeptidase activity." (PMID 39948060, 2025). "The whole-cell proteomics detected 157 differentially expressed proteins, including upregulated IDO1 and legumain (LGMN) in tumor-induced DC3s." (PMID 40789452, 2025). "Given its prominent role in tumor biology, LGMN has been identified as a valuable biomarker for cancer diagnosis and prognosis as well as a promising therapeutic target." (PMID 41375125, 2025). "The role of legumain in cancer is complex and multifaceted, encompassing its involvement in tumor progression, metastasis, and as a target for therapeutic intervention." (PMID 39948060, 2025). "LGMN, the asparaginyl endopeptidase, drives tumor progression by immunosuppressive polarization of macrophages, inhibition of anti-tumor T cell responses, and promoting tumor migration and invasion." (PMID 40789452, 2025). "Intriguingly, the mature form of legumain was found to be significantly diminished in tumor tissues." (PMID 39948060, 2025). "In contrast, immunoblotting revealed an increase in prolegumain and a decrease in mature legumain in tumor tissues compared to adjacent kidney tissues." (PMID 39948060, 2025). "In our study, we collected 16 pairs of tumor and adjacent kidney tissues from patients diagnosed with ccRCC and compared the expression of legumain at both the mRNA and protein levels." (PMID 39948060, 2025). "In this study, we explored the mechanisms of the pro-tumor effect of LGMN, a key protease that is highly expressed by TAMs, the most abundant cells in GBM tumor mass, accounting for up to 50% of its total cells." (PMID 40131864, 2025). "An essential innovation is their legumain-cleavable linker, which maintains stability in circulation yet is specifically cleaved in tumor lysosomes, where legumain is overexpressed." (PMID 41012501, 2025). "In the present study, we compared legumain levels in ccRCC tumor tissues and adjacent normal kidney tissues." (PMID 39948060, 2025). "Extracellular legumain undergoes autoactivation in the acidic tumor microenvironment and participates in the remodeling of the ECM, either by directly hydrolyzing matrix components like fibronectin or by promoting the maturation of MMPs." (PMID 39948060, 2025). "Legumain expression, primarily localized in tubular cells, was found to be diminished in tumor tissues." (PMID 39948060, 2025). "Immunoblotting results showed a reduction of both pro- (approximately 55 kDa) and mature legumain (approximately 32 kDa) in the cell lysates of tumor cells." (PMID 39948060, 2025).
tumor (continued). "Legumain, a lysosomal cysteine protease, is highly expressed in many solid tumors, TAMs and endothelial cells of tumor neovascularization." (PMID 39717759, 2024). "Elevated expression of LGMN in TAMs within GC tissues, and knocking down LGMN expression in TAMs, can effectively suppress tumor growth." (PMID 39065799, 2024). "Recent years have brought a lot of attention to LGMN and its function in the tumor microenvironment." (PMID 36825203, 2023). "This supports the idea that LGMN is a pivotal protein in regulating tumor development, invasion, and dissemination." (PMID 36825203, 2023). "Several types of solid tumors, including those of the breast, colon, prostrate, and ovary, have been found to express LGMN at high levels in tumor neovascular endothelial cells, TAMs inside the tumor stroma, and in the tumors themselves." (PMID 36825203, 2023). "After being translocated into tumor cells, the nanoparticle was disassembled by the cleavage of intracellular abundant enzymes, such as furin, protease, or legumain, resulting in the recovery of the NIR fluorescence for tumor imaging." (PMID 37513233, 2023). "LGMN is a protein that is significantly expressed in a number of tumor disorders, including ovarian, breast, and cervical cancer." (PMID 36825203, 2023). "High LGMN expression in numerous malignant tumor cells has been found to alter prognosis, and several studies have demonstrated that patients with high LGMN expression have a lower relative survival." (PMID 36825203, 2023). "Detecting isolated primary tumor cells demonstrated that LGMN knockout in TAMs inhibited tumor growth, proliferation, and apoptosis." (PMID 36825203, 2023). "When the liposomal nanoparticles were extravasated into tumor tissues via the EPR effect, the AAN moiety was instantly removed by the tumor-overexpressed legumain, restoring TAT’s ability to facilitate the uptake of drug-loaded nanoparticles by cancer cells." (PMID 37544972, 2023). "The high expression level of legumain is related to tumor differentiation, tumor initiation and development, and tumor invasion." (PMID 35399931, 2022). "This legumain-induced hydrolysis also leads to the activation of protease zymogens, which are highly correlated with angiogenesis and other tumor-facilitating functions." (PMID 35203212, 2022). "Legumain, a tumor-associated antigen, has been widely investigated in human oncology to determine its malignant roles and its potential tumor-promoting mechanisms; however, few studies have considered the expression of legumain in tumor-bearing dogs." (PMID 35203212, 2022). "Taken together, the findings show that legumain was overexpressed in the canine tumor samples in this study, and further studies are needed to elucidate these findings with a more comprehensive investigation." (PMID 35203212, 2022). "Legumain-induced protease cascades are highly correlated with coagulation, apoptosis, complement cascades, and other tumor-promoting biological pathways." (PMID 35203212, 2022). "Although further studies on a larger number of cases are necessary to clarify the clinical application of legumain, the overexpression patterns of legumain in canine tumor tissues are reported, for the first time, in this study." (PMID 35203212, 2022). "Legumain is highly abundant in tumor stroma and is also found in the cytoplasm and on the surface of tumor cells." (PMID 35800070, 2022). "Among all the samples, the HGT had the highest expression level of legumain at 57.09% ± 5.10% in the tumor sections." (PMID 35203212, 2022). "In the immunofluorescence assay, legumain expression was mainly localized to the cytoplasm of the tumor cells." (PMID 35800070, 2022). "This study aimed to evaluate the expression of legumain in tumor-bearing dogs, because tumor antigens are useful tools in cancer diagnoses, monitoring, prognoses, and even as therapy targets." (PMID 35203212, 2022).
tumor (continued). "The high levels of legumain expressed by tumor cells suggests that the inhibition of legumain is a potential strategy against tumor progression, based on its facilitation of tumor growth and its specific expression in tumors." (PMID 35203212, 2022). "Because legumain participates in tumor development, legumain has been regarded as an essential biomarker for the tumor diagnosis." (PMID 35631369, 2022). "The anti-legumain polyclonal antibody recognized a dominant band near 54 kDa (NCBI reference sequence: XP_038528856.1) in the canine tumor cell lysates, indicating that this polyclonal antibody can identify the correspondent proteins in the canine species." (PMID 35203212, 2022). "Compared with the normal tissues, all tumor samples displayed high intensities of legumain expression." (PMID 35203212, 2022). "Patients with high levels of ELK1 and LGMN expression in tumor tissues experienced significantly shorter OS than patients with low ELK1 expression (n = 173, p < 0.0001)." (PMID 34966781, 2021). "The use of Salmonella to overexpress tumor antigens in cancer cells, such as Legumain, PCSA, AFP, etc., has also been shown to inhibit tumor growth effectively." (PMID 33717106, 2021). "We found that the LGMN expression was much higher (P < 0.05) in GC patients with stage III/IV compared to GC patients with tumor stage I/II." (PMID 32766126, 2020). "Legumain is a cysteine protease, secreted by tumor cells undergoing hypoxia and also by TAM and is thought to have several roles in cancer pathogenesis." (PMID 31934533, 2019). "In tumors, the overexpression of legumain was found in correlation with angiogenesis, expansion of the tumor, and cleavage of the ECM." (PMID 31934533, 2019). "Legumain expression is increased in tumor cells, and a high expression level of legumain accelerates invasion and metastasis of tumor cells." (PMID 29541256, 2018). "In vivo, results of immunofluorescence staining showed co-localization of legumain and fibronectin in the xenografted tumour tissues, suggesting extracellular localisation of legumain in the tumour microenvironment." (PMID 27464733, 2016). "Administration of the legumain inhibitor to the xenograft DLBCL model suppressed tumour growth, angiogenesis and collagen deposition compared with the control." (PMID 27464733, 2016). "Accumulating data have identified legumain expression in a variety of tumour types, suggesting a role in tumour progression." (PMID 27464733, 2016). "To further explore the effect of legumain expressed by M2 TAMs on the tumour pathogenesis of DLBCL, we established the OCI-Ly3 xenograft mouse model of DLBCL and divided the animals into three groups (n = 5)." (PMID 27464733, 2016). "In this study, co-localization of the M2 TAM marker CD206 and legumain supported that legumain is overexpressed in the tumour microenvironment of DLBCL." (PMID 27464733, 2016). "In this study, we used LGMN as a therapeutic target to observe the anti-tumor effects of radiation-induced LGMN knockdown in BC cells." (PMID 27656894, 2016). "In the xenograft mouse model of DLBCL, decreased fibronectin and collagen I, as well as increased legumain expression and angiogenesis were found at the late stage tumours compared with early stage tumours." (PMID 27464733, 2016). "Our previous study revealed overexpression of a member of the cysteine proteases, legumain, in the tumour microenvironment." (PMID 27464733, 2016). "Administration of a legumain inhibitor or deletion of M2 TAMs limits tumour expansion, ECM cleavage and angiogenesis." (PMID 27464733, 2016).
tumor (continued). "In addition, the inhibitory effect of an isolated carbohydrate fraction of AndoSanTM on the tissue degrading pro-inflammatory and tumor-associated enzyme, legumain (aspariginyl endopeptidase), that probably may also contribute to less inflammatory activity in the CD patients." (PMID 27415795, 2016). "Studies have shown that LGMN not only participates in tumor migration and invasion but also plays important roles in the occurrence and development of tumors; furthermore, it is associated with a poor prognosis in tumor patients." (PMID 27656894, 2016). "Co-localization of legumain and fibronectin was observed in the extracellular matrix of tumour tissues." (PMID 27464733, 2016). "Our results showed that LGMN was overexpressed in tumor tissues, affected cancer development and deterioration, and was associated with poor prognosis in cancer patients." (PMID 26607955, 2015). "Legumain appears to be involved in tumor development and deterioration; thus, it can potentially be developed into both a marker for monitoring and diagnosing tumors and a therapeutic target." (PMID 26607955, 2015). "IMCs in our model also secrete M2 marker proteins including YM1, arginase-1, MRC1 (soluble CD206) and legumain and promote tumour cell growth in vitro and ex vivo (Fig3)." (PMID 26183450, 2015). "LGMN expression is known to correlate with a lower rate of apoptosis, and increased metastasis and tumor invasion." (PMID 24742492, 2014). "Immunohistochemical analysis of paraffin embedded tumor tissue from CRC patients, also revealed heterogeneous expression of legumain which was apparent both in the tumor cells and the surrounding stromal cells." (PMID 23326369, 2013). "Legumain protein expression was elevated in metastasis lymph nodes samples compared with primary tumor samples in 35 of 98 pairs." (PMID 24023813, 2013). "Recent studies reveal that legumain overexpression is detected in the tumor cells themselves in some tumor models." (PMID 23577091, 2013). "After being challenged with 5×104 4T1 tumor cells, the mice were orally vaccinated with the same amount of legumain DNA plasmid loaded in different delivery carriers or with the PBS control." (PMID 23577091, 2013). "Such nanoparticles specifically target cells expressing legumain in their plasma membranes, which is a common property of the tumor microenvironment, especially under hypoxic conditions." (PMID 24014113, 2013). "Legumain is located in the endosomal/lysosomal pathway and cell surfaces of cancer cells, tumor endothelial cells, and TAMs." (PMID 21385454, 2011). "High activity of cysteine proteases such as legumain and the cathepsins have been shown to facilitate growth and invasion of a variety of tumor types." (PMID 20074384, 2010). "In addition to its lysosomal localization, legumain has been reported to be partially expressed on the surface of tumor cells, where it can cleave extracellular substrates." (PMID 41375125, 2025). "LGMN overexpression has been reported in numerous solid tumors, including breast, colorectal, gastric, ovarian, and prostate cancers, and it significantly contributes to tumor progression, invasion, and metastasis." (PMID 41375125, 2025). "Before we begin to explain the action of legumain in tumor-associated macrophages (TAMs), we must first understand that there are two central TAM polarization states in the TME: pro-inflammatory "M1" and pro-tumor "M2"." (PMID 40584290, 2025). "Moreover, this same group also characterized legumain (LGMN) as a key protease that is transcriptionally regulated by HIF1α and enriched in tumor-associated macrophages." (PMID 38994360, 2024). "In the future, efforts should be directed not only toward the production of efficient legumain inhibitors, but also toward the use of legumain for in vivo tumor imaging and therapy, both of which can be targeted in conjunction with legumain to achieve superior therapeutic results." (PMID 36825203, 2023).
tumor (continued). "With the development of molecular biology techniques, the mechanism of LGMN’s involvement in tumor occurrence and development has been gradually studied and revealed, such as exosome transport, regulation of protease activity, regulation of integrin interaction, signaling pathway intervention, etc.." (PMID 36825203, 2023). "Due to the high expression of LGMN in tumor tissues, the precursor drugs specifically activated by LGMN may be selective and tumor-specific." (PMID 36825203, 2023). "Lastly, the expression patterns of legumain in the cytoplasm are correlated with tumor malignancy." (PMID 35203212, 2022). "The overexpression of legumain potentially facilitates tumor formation in dogs with cancer, indicating that legumain could be a potential tumor biomarker and/or therapeutic target, with more investigation." (PMID 35203212, 2022). "In conclusion, this study first identified the heightened levels of legumain in canine tumors, which suggested that legumain may also act as a tumor antigen in the promotion of tumor development." (PMID 35203212, 2022). "Legumain plays an important role in regulating metastasis-related factors in the tumor stroma, but it is unclear whether it plays a role in tumor metastasis-related EMT in NB." (PMID 35800070, 2022). "Thus far, little is known about the biological functions and processes involving legumain in tumor development in dogs." (PMID 35203212, 2022). "Taken together, these results indicated that the vesicular positivity of legumain in the cytoplasm could serve as a potential predictor for tumor malignancy." (PMID 35203212, 2022). "Thus, legumain has been regarded as a candidate tumor antigen that is overexpressed in several types of cancers and facilitates tumor malignancies." (PMID 35203212, 2022). "Furthermore, legumain regulates the remodeling of the extracellular matrix through the initiation of the gelatinase A zymogen which, thereby, promotes tumor progression." (PMID 35203212, 2022). "Legumain is the active form of prolegumain, abundant in tumor plasma." (PMID 35800070, 2022). "Other potential targets on TAMs and tumor cells include legumain and the p32 receptor." (PMID 36365245, 2022). "LGMN is highly expressed in various tumors and can promote tumor progression and invasion." (PMID 36164607, 2022). "Elevated levels of legumain are found in human cancers, and this oncoprotein may facilitate tumor invasion and metastasis when overexpressed." (PMID 35203212, 2022). "The IMR32 cell line is the most malignant type-I form of NB, and the abundant active legumain in IMR32 may also support legumain as a marker of tumor malignancy." (PMID 35800070, 2022). "Previous reports in adult solid tumors indicated a positive correlation between legumain and tumor malignancies, and our research proved legumain could regulate EMT through its AEP activity." (PMID 35800070, 2022). "In addition to its intracellular activity, legumain can be secreted into the tumor microenvironment (TME) in which it contributes to degrading and remodeling the ECM, either by producing the mature forms of MMP2 and MMP9 or by processing cathepsins." (PMID 35067006, 2022). "Cystatin M/E inhibits legumain and cathepsins L and V and acts as a tumour suppressor." (PMID 34322157, 2021). "In group A, VDAC1-ΔC and LGMN were present in tumor (T) tissues, except for patients #7 and #12." (PMID 32194829, 2020). "Additionally, paired analysis of LGMN mRNA expression in 24 matched GC tissues and normal tissues demonstrated that LGMN mRNA expression was significantly increased in tumor tissues compared with normal tissues (P < 0.05)." (PMID 32766126, 2020). "Targeting legumain, a highly overexpressed target molecule on M2 macrophage effectively decreased the release of protumoral growth and angiogenic factors, which in turn, led to suppression of both tumor angiogenesis, tumor growth and metastasis." (PMID 31779710, 2019).